INS (insulin)
Diseases named in the same sentence as INS in open-access papers (continued):
Sharing a sentence is not in itself a finding about the gene and the disease.
Obesity (continued). "Thus, given that adipose tissue is a target for therapeutic intervention in obesity and age-related diseases, in this work, we examined the effect of HEL in PA-treated human SW872 adipocytes by assessing insulin signaling, glucose uptake and inflammatory marker content." (PMID 38794136, 2024). "This study explores the scope of construing the role of these two diametrically opposing hormones on the glucose level not just in obesity but in different glucose tolerance states by looking at the hormone levels and at the insulin glucagon bipolar axis itself." (PMID 38665134, 2024). "However, the present study did not report any associations between cumulative MVPA and cumulative insulin or HOMA-IR from childhood through young adulthood, irrespective of sex and obesity status." (PMID 38441224, 2024). "Obesity and insulin usage were also demonstrated to have a negative effect on HRQoL." (PMID 37033039, 2023). "Therefore, IMCL-T reflected insulin sensitivity; however, IMCL-S was related to obesity." (PMID 36810530, 2023). "Despite insulin acutely lowering AIx75 and pulse wave velocity in healthy individuals, there is reduced endothelial responsiveness in some, but not all, studies of adults with obesity." (PMID 36837756, 2023). "Regulating insulin levels early in childhood before the onset of the early weight gain may be key in modulating the onset and severity of obesity and hyperphagia in individuals with PWS, as well as in other young children with non‐PWS early‐onset obesity." (PMID 37546289, 2023). "On the contrary, suppression of insulin secretion resulted in increased INB levels, consistent with the hypothesis that insulin negatively regulates INB and may explain the inverse relationship between BMI and INB in women with obesity and raised insulin levels." (PMID 37272254, 2023). "In contrast, no significant changes in blood glucose, insulin, and lipid profiles were observed in sedentary individuals, overweight individuals and/or individuals with obesity between passive hypoxic (~ 5700 m; three 1-h sessions per week for 8 weeks) and normoxic exposure." (PMID 36441492, 2023). "Through its indirect effects on insulin signaling, its influence on adipocyte differentiation, and its control over the recruitment of inflammatory cells within adipose tissue, PAI-1 may play multiple roles in the development of obesity." (PMID 37237937, 2023). "Initially, Reaven did not include obesity in his description of syndrome X since he could identify non-obese people with IR and people with obesity who were insulin sensitive." (PMID 36832102, 2023). "Increased amino acid supply from skeletal muscle through muscle GR is thought to play an important role in enhancing hyperinsulinemia, but other mechanisms, including impairment of muscle insulin signaling via muscle GR, may also be involved in CORT-induced obesity." (PMID 36917179, 2023). "In another acute trial, adults with overweight/obesity (n = 54) were randomized to consume either mixed nuts or pretzels and showed pretzel consumption increased glucose and insulin, whereas, with mixed nuts, no elevation was detected at 60 min post snack consumption." (PMID 36839236, 2023). "Obesity is known to increase plasma TG levels, but after starting a calorie-restricted diet TG concentrations generally decrease, mainly due to a reduction in VLDL-TG synthesis, consequent to a low substrate availability and reduced circulating insulin concentrations." (PMID 37892400, 2023). "After stratification by obesity status, blood hemoglobin (r = −0.36, p = 0.019), haematocrit (r = −0.44, p = 0.003) and ultrasensitive CRP (r = −0.37, p = 0.016) were significantly associated with the change in insulin sensitivity in subjects without obesity." (PMID 36902180, 2023). "Therefore, our results indicated that insulin sensitivity was decreased in FGR rats during childhood without obesity." (PMID 36649006, 2023).
Obesity (continued). "This insulin-centric approach could also help resolve the main weakness of the healthy obesity concept, namely that there is no clear definition of what “healthy” actually means in this context." (PMID 36823293, 2023). "However, Koreans are often unable to increase pancreatic insulin secretion sufficiently, regardless of obesity." (PMID 37957738, 2023). "However, the concentrations of LH are not affected by IR, insulin concentrations or obesity in mares, so most studies conclude that ID is most likely not the main cause for the emergence of anovulatory follicles." (PMID 37152686, 2023). "In a follow-up study of children (ages 5–10) born to women who participated in a multicenter trial, there was no reduction found in obesity or metabolic dysfunction in the offspring of women who received treatment (diet therapy and insulin if necessary) compared to those with mild untreated GDM29." (PMID 37626162, 2023). "This may suggest that INS and BRD2 play an important role in BC patients with obesity." (PMID 37895140, 2023). "The consumption of Obex® together with lifestyle changes increased HDL-c, contributed to a rapid reduction of weight and waist circumference, as well as improved insulin homeostasis, which did not occur in the placebo group, and appears to be safe as an adjunct at conventional obesity treatment." (PMID 36804035, 2023). "In conclusion, the present study reveals a previously unrecognized role of diosmin, a conventional drug features long-time clinical use and safeness, in improving insulin sensitivity by blocking PPARγ phosphorylation and reducing obesity without the side effects of classic PPARγ full agonists." (PMID 36841479, 2023). "Furthermore, CGA, unlike thiazolidinediones (TZDs) or insulin, does not induce obesity or other side effects." (PMID 38068801, 2023). "However, our study showed no improvement in all obesity-related indicators, such as lipid profile, blood glucose, insulin index, abdominal visceral fat CT, and body composition analysis results after Cheonggukjang pill administration." (PMID 37297435, 2023). "Finally, a recent study evaluated reactive hypoglycemia, snacking habits, and obesity in relation to the index of glucose effectiveness (i.e., the ability to increase peripheral glucose uptake independent of insulin)." (PMID 37726785, 2023). "TSH is involved in obesity through 1) insulin inhibited deodinase (less T3, high T4), which provides no negative feedback and resulting in high TSH, and 2) leptin is a stimulator of TRH (hypothalamus) which could increase TSH." (PMID 38720938, 2023). "Furthermore, BMI does not correctly capture the subset of patients with ‘metabolically healthy’ obesity, who do not experience the expected metabolic complications of obesity, most likely due to less visceral fat and preserved insulin sensitivity." (PMID 37428558, 2023). "We examined the relationship between sleep parameters and adipose tissue insulin sensitivity in non-diabetic participants with obesity and newly diagnosed OSA who underwent overnight polysomnography and a 2 h oral glucose tolerance test during which circulating free fatty acids were measured." (PMID 39434962, 2023). "Recent studies show that hyperinsulinemia may not initiate obesity hypertension itself, but rather decreased insulin sensitivity which is a trigger for hyperglycemia and dyslipidemia." (PMID 37071287, 2023). "Early animal studies suggested that administration of monacolin K might be beneficial in experimental models of NAFLD by improving insulin sensitivity and decreasing obesity-related inflammation, but human studies are lacking." (PMID 37111106, 2023). "OSA might impair beta-cell function reducing the pool of promptly releasable insulin in children and adolescents with obesity, in the absence of an effect on insulin sensitivity." (PMID 36670156, 2023).
Obesity (continued). "This hypothesis is supported by data on Otsuka Long-Evans Tokushima Fatty (OLETF) rats, an animal model of type 2 diabetes with obesity, hence long-term administration of recombinant PEDF significantly improved body weight, metabolic parameters and insulin resistance." (PMID 36837889, 2023). "This is consistent with findings in the present study among sedentary adults with RH, as neither baseline obesity (P = .656) nor insulin sensitivity (P = .444) moderated treatment changes on Executive Function, despite both associating with baseline hsCRP concentrations." (PMID 36541028, 2023). "Further, the progression of HFD-induced overweight/obesity and the metabolic syndrome are both attenuated by pharmacological or genetic reduction of plasma insulin responses to feeding or by inhibition of insulin signaling, without evident changes in net daily energy intake." (PMID 37819196, 2023). "Hence, T1D mice exhibited hyperglycemia without obesity, despite daily insulin treatment, which is consistent with a previous report." (PMID 37078449, 2023). "In obesity, adipocytes predominantly secrete proinflammatory adipokines that further promote adipose tissue dysfunction with negative effects on local and systemic insulin sensitivity." (PMID 37152954, 2023). "Finally, the use of metformin as an adjunct therapy to insulin was higher in patients with overweight/obesity, mainly females (data not shown)." (PMID 36823646, 2023). "Other than indices of obesity, in this study there were significant differences in some of the anthropometric and biochemical parameters in the case and control groups, including SBP, DBP, HDL-C, FPG, insulin, and HOMA-IR, which could be attributed to the obesity." (PMID 37862340, 2023). "Exercise training, particularly aerobic and combined exercise has beneficial effects on fasting insulin and glucose levels, HOMA-IR and BW in children and adolescents with overweight or obesity, and could provide an important adjunct therapy to control IR and related outcomes." (PMID 37635963, 2023). "These patients used higher daily insulin doses, were more frequently using metformin, anti-hypertensive drugs, and statin, had more frequently a family history of overweight/obesity, T2D, hypertension, and coronary disease without difference in the prevalence of DR and CKD." (PMID 36823646, 2023). "Contraction-stimulated, AMPK-independent mechanisms for Rac1 activation may also be different from those in insulin signaling and may not be inhibited by obesity." (PMID 37511290, 2023). "This double-blinded, randomised clinical trial examined the effects of an extract of unripe avocado that was naturally enriched in MH on glucose tolerance, insulin response, lipids, hsCRP and F2-isoprostanes as markers of oxidative stress, and autophagy in nondiabetic individuals with obesity." (PMID 38004206, 2023). "Even so, the risk of kidney stones was significantly higher in MHO individuals than in those with MHN, which validated the hypothesis that obesity can contribute to kidney stones formation even in the absence of metabolic abnormalities and insulin resistance." (PMID 37304121, 2023). "A recent human study of 11 men with obesity in a randomized cross-over design demonstrated that short-term TRF was sufficient to modulate rhythmic metabolism of lipids, amino acids and improve nocturnal glucose levels and insulin profiles in skeletal muscle during daytime." (PMID 36810287, 2023). "The favorable influence of SAT on metabolic homeostasis has been experimentally demonstrated by the improvement in insulin sensitivity, plasma lipid profiles, and hepatic lipid content after autologous transplantation of SAT into VAT depots in rodent models of diet-induced obesity." (PMID 36782211, 2023).
Obesity (continued). "In mice with HFD-induced obesity, DW2010 induced AMP-activated protein kinase activation in the intestine and liver by inhibiting the gut microbiota and endotoxin production; furthermore, it suppressed body weight, hyperglycemia, epididymal fat, and insulin levels." (PMID 37447399, 2023). "There are reports that INS may not have an influence on the secretion of IR, regardless of the concentration, in people with INS resistance or obesity." (PMID 36615169, 2023). "Interestingly, H19 overexpressing mice showed a protective effect against diet-induced obesity and improved insulin sensitivity in brown but not in white adipocytes." (PMID 36672953, 2023). "Furthermore, female APOE∗3-Leiden.CETP mice are not prone to develop obesity and related pathologies, such as insulin resistance and intramuscular lipid accumulation." (PMID 37356205, 2023). "However, another meta-analysis revealed that synbiotic supplementation in individuals with overweight or obesity merely decreased fasting insulin without any significant effects on other glycemic indices." (PMID 37929031, 2023). "Additionally, we did not measure insulin levels or estrogen levels, as the focus of our study was the relationship between obesity, adiposity measures, and oxidative stress." (PMID 37190046, 2023). "Notably, brothers/sons of women with PCOS have elevated androgen levels, increased total cholesterol and low density lipoproteins levels at puberty, decreased insulin sensitivity (independent of obesity) and glucose tolerance, among other symptoms." (PMID 37223019, 2023). "On the other hand, treatment with ESGA at increasing doses of 50, 100, and 200 mg/kg, failed to attenuate or reverse obesity and did not prevent increases in fat pad accumulation, glucose and insulin levels, HOMA-IR levels, or the circulatory levels of leptin in HFD-fed rats." (PMID 38004149, 2023). "Also, in mice fed a HFD to induce obesity, we found that IMC treatment significantly altered the oscillatory patterns of key host metabolic hormones insulin, leptin, and adiponectin, which is likely to play a modulatory role in downstream lipid metabolic phenotypes." (PMID 35072627, 2022). "Moreover, fasting insulin level and HOMA-IR were significantly elevated in hypothyroid children and adolescents with obesity compared to lean hypothyroid children and adolescents which reflects the additive role of obesity in the development of IR in hypothyroid children with obesity." (PMID 35501770, 2022). "Furthermore, insulin clearance was not different between lean people and people with obesity who were as insulin sensitive as lean people." (PMID 35054781, 2022). "The fact that a more intensive insulin therapy is related to weight gain could go some way to explaining why obesity does not clearly worsen metabolic control." (PMID 36531459, 2022). "Individuals living with obesity had significantly greater BMI, waist circumference, hip circumference, % body fat, body fat mass (kg), and higher blood concentrations of TG, total cholesterol, LDL-C, glucose, and insulin, in comparison to normal weight individuals." (PMID 35958557, 2022). "Importantly, the sequencing data presented here supported our preexisting hypothesis that obesity may result in activation of SGK1-related pathways, and we demonstrated increased insulin signaling, mineralocorticoid signaling, and mTOR signaling." (PMID 35998035, 2022). "From 2007 to 2018 the proportion of children and adolescents receiving higher doses of insulin and using insulin analogs continued to increase to 100% in 2018, but the prevalence of overweight and obesity observed did not change from 2007 to 2018, in contrast to other studies." (PMID 35549683, 2022).
Obesity (continued). "Specifically, under sex hormone-deprived condition, females are generally more susceptible to develop metabolic disorders, whereas males are more susceptible to develop cardiac autonomic, LV and mitochondrial dysfunction even in the absence of obesity and insulin-resistant condition." (PMID 35301277, 2022). "However, in obesity adipose tissue, ATM polarity shifts towards the proinflammatory M1-like phenotype, and this shift leads to the secretion of pro-inflammatory cytokines, which can impair the insulin signal transduction and promote insulin resistance." (PMID 36012516, 2022). "We suspected that this may be due to the fact that the experimental animals did not develop full obesity or to the effect of the tested ligands on H3R present in pancreatic β cells responsible for insulin secretion and blood glucose regulation." (PMID 35806019, 2022). "Therefore, evidence to date does not describe clear role of resistance to the action of insulin in muscle in modifying protein turnover in skeletal muscle of humans with obesity." (PMID 35350688, 2022). "However, three weeks of consuming the obesogenic WD was not sufficient to significantly alter critical peripheral obesity biomarkers, including leptin, insulin, triglycerides, and corticosterone (p > 0.05)." (PMID 35220393, 2022). "However, there have now been several reports of individuals with significant obesity but little, or no, difference in metabolic parameters such as insulin resistance when compared to a lean healthy group of individuals." (PMID 36394259, 2022). "The effects of IN insulin on food intake in women with obesity have not yet been examined." (PMID 35397638, 2022). "The higher muscle mass of men, compared with women, may contribute to the lower effect of obesity on T2DM, because skeletal muscle, responsible for the majority of basal and insulin-stimulated glucose uptake, plays a critical role in regulating glucose homeostasis." (PMID 35443612, 2022). "We also reported that the adipose SRA1 expression was higher in non-diabetic persons with obesity compared with non-diabetic lean participants, and that the changes associated directly with BMI, PBF, fasting serum insulin, HOMA-IR, certain inflammatory markers but inversely with HbA1c level." (PMID 36552771, 2022). "The tendency of hyperinsulinemia in the youths, when compared with similar levels of obesity and dysglyceamia in adults, may suggest that the greater amount of insulin released may not represent more “robust” pancreatic function." (PMID 36536359, 2022). "This insight into leptin and insulin signaling in HRA neurons led them to hypothesize that hyperleptinemia in obese-induced mice might lead to an imbalance between leptin and insulin signaling in HRA neurons and, consequently, affect the regulation of glucose homeostasis in obesity." (PMID 36290695, 2022). "No study has measured the effect of obesity surgery on cephalic insulin release." (PMID 35215515, 2022). "However high-fat diet-induced obesity in rodents produces an insulin resistant, prediabetes phenotype, but not a true T2D phenotype while lacking notable cardiac dysfunction." (PMID 35657616, 2022). "In the case of obesity, it has been previously demonstrated that cytokine production by expanded AT leads to high serum levels of proinflammatory cytokines, which in turn induce the activation of IKKβ/NFκB and JNK pathways, leading to insulin resistance in adipocytes and hepatocytes." (PMID 35321537, 2022). "Ghrelin suppresses insulin secretion by regulating uncoupling protein 2 (UCP2) in panarctic β cells; ghrelin ablation attenuates hyperglycemia of leptin-deficient ob/ob mice without affecting obesity." (PMID 35454071, 2022). "In addition, we found that the intervention effects in the MPC group were prominent in patients with younger age, obesity, higher C-peptide levels, and no insulin treatment." (PMID 35900817, 2022).